FLG (filaggrin)
Diseases named in the same sentence as FLG in open-access papers (continued):
Sharing a sentence is not in itself a finding about the gene and the disease.
asthma (85 papers, 2009 to 2026). "For instance, FLG mutations not only affect skin hydration but also increase the risk of allergic conditions like asthma and hay fever, demonstrating their broader systemic impact." (PMID 40529811, 2025). "FLG mutations are associated with early-onset, persistent eczema, and increased risk of asthma, allergic rhinitis, and multiple allergic sensitizations." (PMID 40529811, 2025). "FLG mutations with suppressed levels of FLG expression predispose to AD, but are also associated with other diseases, including asthma, irritant and allergic contact dermatitis, and alopecia areata." (PMID 40141720, 2025). "Loss-of-function mutations in the FLG gene, which encodes filaggrin, are associated with increased susceptibility to asthma, elevated IgE levels, and particularly with impaired skin barrier function." (PMID 40818974, 2025). "These include MUTYH and colorectal cancer, GJB2 and hearing loss, and a pleiotropic association of FLG with both dermatitis and asthma." (PMID 38944039, 2024). "Genetic phase contributes to disease risk for gene-trait pairs: ATP2C2-COPD (p = 0.000238), FLG-asthma (p = 0.00205), and USH2A-visual impairment (p = 0.0084)." (PMID 38944039, 2024). "For instance, FLG was found in both gene-based (OR = 1.01) and single-variant-based (OR = 1.22) analyses for asthma." (PMID 39009607, 2024). "Mutations in filaggrin have been reported to be the main cause of AD, asthma, and allergic rhinitis." (PMID 37513335, 2023). "A study on filaggrin (FLG) loss-of-function mutations highlighted its role in the pathogenesis of asthma and food sensitization." (PMID 36362786, 2022). "Since the genetic association of SNPs in FLG gene and asthma has been concerned in previous researches, we analyzed the biological function of FLG rs75235053 C>G and rs192116923 T>G by bioinformatics tools." (PMID 34484176, 2021). "FLG loss-of-function mutations firstly found in ichthyosis vulgaris patients were related to AD or eczema, food allergy, asthma and hay fever." (PMID 34484176, 2021). "Population studies to date have primarily focused on the relationship between FLG mutations and AD; the relevance of atopic sensitization, allergic rhinitis, and asthma on FLG mutations has also been investigated." (PMID 32536107, 2020). "Although FLG-LOF mutations were an independent risk factor for asthma development in some studies, these mutations have a higher impact as risk factors for asthma development among AD patients." (PMID 32536107, 2020). "A population birth cohort study in the UK with 1.456 newborns followed children until the age of 18 years and found an increased risk of eczema and asthma (RR 2.41, p < 0.001) in patients with a filaggrin mutation." (PMID 30524933, 2018). "Filaggrin deficiency is one of the top genome-wide genetic determinants of asthma, along with the variants found that regulate ORMDL3 expression." (PMID 30473631, 2018). "Filaggrin loss-of-function mutations are a major genetic predisposer for the development of AD and progression to AD-associated asthma." (PMID 26299987, 2016). "We think it is important to point out that our study was prepared from the outset to assess the influence of these mutations and SNPs in the filaggrin gene in asthma and potential importance of atopy in this association." (PMID 27462351, 2016). "The filaggrin mutations predisposing to asthma, allergic rhinitis, and allergic sensitization only in the presence of AD strongly support the role of filaggrin in the pathogenesis of AD and in the subsequent progression along the atopic march." (PMID 25419479, 2014). "One study showed a significant association of two filaggrin gene mutations with asthma and allergic rhinitis, but this association was only seen in subjects with the co-existence of AD and was not apparent in subjects without concomitant AD." (PMID 25419479, 2014).
asthma (continued). "In studies of filaggrin-deficient children, increased transepidermal water loss along with development of specific IgE antibody to dust mite and cat was found with asthma." (PMID 22619686, 2012). "Among markers associated with allergic diseases, mutations in the FLG gene, a protein essential for the skin barrier function, are hypothesized to contribute to asthma." (PMID 36670639, 2022). "In conclusion, in the Th2 cytokine milieu of asthma, FLG deficient mutation in airway epithelial cells may increase the epithelial permeability and the expression of IL-33/TSLP which positively feedback the Th2 inflammation response." (PMID 34484176, 2021). "All these findings support the idea that FLG mutations lead to functional epidermal barrier defects, increasing skin permeability and subsequent allergic sensitization, promoting the Th2 inflammatory response, and eventually leading to asthma." (PMID 32325630, 2020). "It is important to remember that FLG mutations as such also represent a risk factor for other atopic manifestations, e.g., asthma, suggesting that FLG deficiency may have a broader systemic significance." (PMID 32899887, 2020). "Case control, family and population studies and/or other FLG mutations, which then followed, more clearly indicate the meaning of a defective epidermal barrier in pathogenesis, primarily AD, and then other atopic disorders – AR and asthma." (PMID 31223255, 2019). "In addition, the barrier defect has also seen in filaggrin null which carriers also appears to lead to increased asthma susceptibility and exacerbations." (PMID 30473631, 2018). "Filaggrin mutations have been identified as the major genetic predisposer to AD development and in the context of the atopic march, the subsequent progression to AD-associated asthma." (PMID 26299987, 2016). "Interestingly, AD is commonly the first manifestation of allergic disease and filaggrin deficiency is a risk factor for the transition from AD to other atopic diseases such as food allergy, hay fever, and asthma." (PMID 25757221, 2015). "We have shown that early exposure to peanut antigen in household dust is a risk factor for the development of peanut sensitization and clinically confirmed peanut allergy in children who carry a filaggrin (FLG) null mutation in the Manchester Asthma and Allergy Study cohort." (PMID 25457149, 2015). "The discovery of filaggrin mutations is a new key research area that might hold the key to primary prevention of asthma." (PMID 26557262, 2015). "The relationship among AD, asthma, AR and FLG mutations is complex." (PMID 24858702, 2014). "The fact that asthma is found only in a subset of filaggrin mutation carriers with AD supports the hypotheses that asthma is secondary to allergic sensitization that occurs after epidermal skin barrier impairment." (PMID 25419479, 2014). "AD patients carrying filaggrin mutations are significantly associated with the extrinsic form of the disease (IgE-mediated sensitization to inhalant or food allergens), and the development of allergic rhinitis and asthma." (PMID 25419479, 2014). "Recently, it has been shown that filaggrin mutations affect asthma, which supports the hypothesis that impaired skin function acts as a gateway for allergens, increasing the risk of atopic airways diseases." (PMID 22839963, 2012). "The International Study of Asthma and Allergies in Childhood showed that in a group of German children the presence of filaggrin variants increased more than 3 times the risk of developing AD and more than 2 times the risk of developing rhinitis regardless of the presence of AD." (PMID 21941575, 2011). "There is experimental evidence in support of this hypothesis from mouse models as well as clinical epidemiologic studies showing that FLG null mutations are a risk factor for asthma only in the subtype of asthma that is associated with AD." (PMID 21377035, 2011).
asthma (continued). "Importantly, both loss-of-function mutations and SNPs of the FLG gene are also a risk factor for other atopic conditions, e.g., asthma and hay fever thus suggesting that FLG deficiency may have a broader systemic significance." (PMID 34882715, 2021). "Decreased compliance in filaggrin-deficient mice was associated with increased collagen deposition and eosinophil and neutrophil infiltration of the lungs with mixed type 2 and type 17 inflammatory responses, reflecting aspects of pulmonary pathology associated with multiple asthma phenotypes." (PMID 26299987, 2016). "However, whether FLG variants are associated with the progression of asthma to AD deserves further study." (PMID 26448767, 2015). "The differentially expressed genes included those related to inflammation (CCL22, CXCL16, AREG, MMP12) involved in asthma pathophysiology, as well as genes associated with the skin barrier (IVL, CDSN, SPINK5, FLG)." (PMID 39451560, 2024). "The more persistent classes (persistent and late resolution) were most strongly related with filaggrin (FLG)-null mutations and showed the greatest risk of coexistence of asthma, high IgE levels, and parental history of atopy." (PMID 35455494, 2022). "Mucin-7, Mucin-5B, Immunoglobulin J chain, polymeric immunoglobulin receptor, filaggrin and hornerin were differentially altered in asthma and asthma with chronic rhinosinusitis condition compared to control." (PMID 34414402, 2021). "It has been reported that filaggrin can be depressed by Th2 cytokines such as IL-4 which play an important role in the pathogenesis of asthma and AD." (PMID 34484176, 2021). "To evaluate the function of filaggrin in bronchial cells upon the on-set of asthma, we simulated the cytokine environment in asthma with Th2 cytokine IL-4." (PMID 34484176, 2021). "Two candidate gene studies have suggested an interaction between active tobacco smoking and genetic variants in the occurrence of asthma in adults, i.e. the genes thymic stromal lymphopoietin (TSLP) and filaggrin (FLG)." (PMID 28253294, 2017). "Given the perception that the link between AD and asthma is causal it might also be interesting to address the leaky barrier hypothesis further in the context of defects in other structural epidermal and epithelial (airway or gut) proteins, apart from filaggrin." (PMID 26448767, 2015). "We also found our genetic data replicated previous associations with childhood onset suggesting signals at the FLG and IKZF3 loci may drive childhood asthma." (PMID 40105091, 2025). "A GWAS study has identified immune-related gene variants (e.g., FLG and GSDMB) shared by asthma, hay fever and AD, suggesting that these allergic diseases may share the same mechanism that leads to dysregulation of immune-related genes." (PMID 36245730, 2022). "Loss-of-function mutations in the gene encoding filaggrin (FLG) are present in up to 50% of patients with moderate-to-severe AD9, 10 and have been shown to increase the risk of inhalant allergic sensitization, allergic rhinitis, asthma, and peanut allergy." (PMID 25282568, 2014). "In support of this, in spite of the fact that filaggrin, which is known to be crucial for formation of epidermal barriers, is expressed in the skin but not in the lung, genetic deficiency of filaggrin resulted in increased susceptibility to asthma as well as peanut allergy." (PMID 26230091, 2015). "Although some studies proposed that filaggrin expression was absent in the upper airway epithelial cells in both healthy controls and asthma patients, in our study it showed opposite results." (PMID 34484176, 2021). "Furthermore, filaggrin deficiency could intensify the Th2 responses by induction of inflammatory molecules IL-33 and TSLP under the Th2 condition, which forms a positive feedback regulatory loop to amplify the immune response and promotes the progression of asthma." (PMID 34484176, 2021).
asthma (continued). "Furthermore, several genes (SH3KBP1, CRNN, FLG, S100A7A) related to allergic inflammation were either induced in allergic rhinitis patients with or without asthma (SH3KB1) or in allergic rhinitis patients only (CRNN, FLG, S100A7A)." (PMID 24475887, 2014).
psoriasis (69 papers, 2007 to 2026). An autoimmune condition characterized by red, well-delineated plaques with silvery scales that are usually on the extensor surfaces and scalp. "Studies have implied that HLA-C*06:02 (on PSORS1 6p21.33) is a major susceptibility gene locus for psoriasis, whereas null mutations of the FLG gene (1q21.3) have been suggested to increase the risk of AD." (PMID 40920623, 2025). "This limitation also prevents exploration of benefits in specific subgroups, such as patients with particular filaggrin mutations or severe forms of psoriasis." (PMID 41304102, 2025). "In the psoriasis–AD overlap, cytokines linked to Th1, Th17, and Th22 responses in psoriasis help downregulate the expression of filaggrin (FLG), loricrin (LOR), and involucrin (IVL)." (PMID 39859462, 2025). "The epidermal differentiation complex on chromosome 1q21.3 contains FLG gene mutations for AD, and it seems to increase the risk of developing psoriasis in Taiwanese and Chinese populations." (PMID 39859462, 2025). "Particularly in European populations, HLA-C06:02 demonstrates a strong association with psoriasis, with an odds ratio of approximately 3.5, while FLG null mutations are found in up to 50% of moderate-to-severe AD patients of European descent." (PMID 40920623, 2025). "Nevertheless, other FLG genetic variants have been confirmed to confer susceptibility to psoriasis, especially in the Chinese population, indicating a shared region on the genome between AD and psoriasis." (PMID 40920623, 2025). "Regarding association of Filaggrin with the studied clinicopathological parameters, a statistically significant relationship between high Filaggrin in psoriasis skin epidermis and mild psoriasis severity was found." (PMID 38907248, 2024). "The abnormal expression of FLG is associated with disruption of the skin barrier and pathogenesis of inflammatory skin diseases, such as AD and psoriasis." (PMID 39274912, 2024). "In human and mice, decreased Filaggrin expression was associated with abnormalities in epidermal barrier and involved in psoriasis pathogenesis." (PMID 38907248, 2024). "In psoriasis–AD overlap, the cytokines associated with Th1, Th17, and Th22 responses in psoriasis are beneficial to downregulating the expression of FLG, LOR, and IVL." (PMID 38606161, 2024). "Although it is generally believed that the FLG gene mutation contained in the epidermal differentiation complex (EDC) on chromosome 1Q21.3 is more closely related to the development of AD than psoriasis." (PMID 36314037, 2022). "Since the expressions of the pro-inflammatory cytokines (AQP3 and FLG) were suppressed by PPPs in IMQ-induced psoriasis, the underlying mechanism of their anti-psoriatic effects was further explored." (PMID 35153762, 2021). "OVOL1 and Filaggrin might be involved in psoriasis-associated inflammation and skin hyperproliferation." (PMID 38907248, 2024). "However, the results obtained from recent studies challenge this notion, which suggests a broader role of FLG beyond AD condition and its potential association with psoriasis." (PMID 38606161, 2024). "In conclusion, OVOL1 and filaggrin might be involved in psoriasis-associated inflammation and skin proliferation." (PMID 38907248, 2024). "Furthermore, FLG variants participate in susceptibility to psoriasis, as well as other autoimmune and skin disorders." (PMID 37730603, 2023). "In psoriasis, keratinocyte proliferation and differentiation can be interfered with mutations in keratin, as well as decreased expression of the epidermal differentiation markers loricrin and FLG." (PMID 36314037, 2022). "In addition, previous studies also found that psoriasis is often accompanied by a decreased expression of FLG, suggesting that impaired epidermal barrier function is associated with psoriasis." (PMID 36467042, 2022).
psoriasis (continued). "Additionally, filaggrin, another major structural cornification protein is mutated in some psoriasis patients, and the skin lesions in the majority of psoriasis patients and murine models exhibit reduced and abnormal diffused filaggrin protein expression." (PMID 36741386, 2022). "In the psoriasis model, Th1 and Th17 cytokines caused thickening of the stratum corneum, which was accompanied by decreases in the mRNA expression of epidermal differentiation proteins filaggrin (FLG) and loricrin (LOR), and upregulation in hBD-2 and SKALP protein expression." (PMID 32509598, 2020). "Indeed, an S. pyogenes-mediated dominant Th17 response via cutaneous lymphocyte antigen-positive T cell-dependent epidermal cell activation has been implicated in the features of keratinocytes in psoriasis, such as IL-17 production, and decreased filaggrin and loricrin expression." (PMID 29416987, 2018). "Gene expression analysis revealed that the extract restored the expression of the skin barrier molecule filaggrin, reduced the expression of inflammatory markers and inhibited the psoriasis-typical overexpression of antimicrobial peptides." (PMID 42050003, 2026). "Alterations in keratins such as K17 in psoriasis and K6 in AD, or in proteins like filaggrin and loricrin, can dysregulate local immune responses, fostering Th2 or Th17 polarization depending on the context." (PMID 41517378, 2025). "In this study, a significant stepwise reduction in Filaggrin immunostaining from normal to peri-lesional and psoriasis skin was recorded." (PMID 38907248, 2024). "We found a strong downregulation of filaggrin expression in the AD and psoriasis models compared to that in the untreated control models, as well as changes in the expression of loricrin and elafin in the psoriasis and AD models." (PMID 38251799, 2024). "OVOL1 and Filaggrin expression in psoriasis skin epidermis demonstrated a statistically significant negative correlation with PASI score." (PMID 38907248, 2024). "OVOL1 and Filaggrin expression in epidermis showed a significant gradual reduction from normal skin to peri-lesional and psoriasis biopsies (P < 0.001)." (PMID 38907248, 2024). "Concerning the pathogenesis of psoriasis, attention is also paid to the physiological citrullination of keratin proteins and filaggrin, which allows for the preservation of the barrier function of the epidermis." (PMID 39409000, 2024). "There was a statistically significant relationship between high epidermal mean percent of positive cells of Filaggrin in lesional skin and mild psoriasis severity (p = 0.045)." (PMID 38907248, 2024). "This work aims to search the immunohistochemical expression and correlation between OVOL1 and Filaggrin in psoriasis." (PMID 38907248, 2024). "As expected in an inflammatory skin disease, both AD and psoriasis models showed disturbed epidermal differentiation with decreased protein and mRNA expression of the late keratinocyte differentiation markers filaggrin (FLG) and loricrin." (PMID 38251799, 2024). "OVOL1 demonstrated a significant direct correlation with Filaggrin expression in psoriasis (r = 0.568, P < 0.004)." (PMID 38907248, 2024). "Loricrin (LOR) was the most significantly downregulated gene in the psoriasis lesions, and filaggrin (FLG, FLG2) was also strongly downregulated." (PMID 36841845, 2023). "Some of these findings closely paralleled observations in psoriasis cases, marked by decreased loricrin and filaggrin protein expression." (PMID 38139083, 2023). "Filaggrin and loricrin, which participate in the formation of epidermal cornified envelopes, are decreased in psoriasis, whereas involucrin, another envelope precursor, is overexpressed in psoriasis lesions." (PMID 37111171, 2023).